DACH1 (dachshund family transcription factor 1)
Diseases named in the same sentence as DACH1 in open-access papers (continued):
Sharing a sentence is not in itself a finding about the gene and the disease.
infection (1 paper, 2016). The state of being infected such as from the introduction of a foreign agent such as serum, vaccine, antigenic substance or organism. "We, also, further detected the cell cycle-related proteins change of podocytes under the infections the plasmid of DACH1." (PMID 27888806, 2016). "At 48 hours post-infection with DACH1 or control plasmid, DACH1 was significantly upregulated by immunofluorescence and western blotting analysis." (PMID 27888806, 2016).
metabolic disease (1 paper, 2020). A congenital disorder (due to inherited enzyme abnormality) or acquired (due to failure of a metabolically important organ) disorder resulting from an abnormal metabolic process. "Accordingly, suppression of DACH1 using hepatocyte-targeted siRNA strategies, a modality that has been approved for use in humans, may provide an integrated approach to the problem of hepatocyte-mediated perturbations in metabolic disease." (PMID 32657780, 2020).
DACH1 also shares sentences with these, for which no sentence is quoted: adenocarcinoma (3 papers); Cardiovascular Disease (2); coronary arteriosclerosis (2); glomerulopathy (2); liver cancer (2); pancreatic ductal adenocarcinoma (2); renal cell carcinoma (2); Sepsis (2); carcinosarcoma (1); chordoma (1); Cirrhosis (1); co-infection (1); colon cancer (1); colorectal adenocarcinoma (1); colorectal tumors (1); cutaneous melanoma (1); diseases of the endocrine system (1); Fraser syndrome (1); granular cell carcinoma (1); hemangioma (1); Hepatic steatosis (1); Hip dysplasia (1); hydronephrosis (1); influenza (1); invasive breast carcinoma (1); laryngeal squamous cell carcinoma (1); LIG4 syndrome (1); liver cirrhosis (1); Lynch syndrome (1); melanoma (1).
A further 9 diseases each share a sentence with DACH1 in 1 paper.